ATP8B1 (ATPase phospholipid transporting 8B1)
Diseases named in the same sentence as ATP8B1 in open-access papers (continued):
Sharing a sentence is not in itself a finding about the gene and the disease.
intrahepatic cholestasis (23 papers, 2010 to 2025). A cholestasis characterized by impairment of the bile flow caused by obstruction located in the liver. "Humans with the Atp8b1 mutation have progressive intrahepatic cholestasis and are prone to pneumonias." (PMID 35204783, 2022). "ATP8B1 deficient patients suffer from intrahepatic cholestasis, often accompanied with extrahepatic symptoms including diarrhoea, pancreatitis and hearing problems." (PMID 23251605, 2012). "Overall, we provided evidence that intrahepatic cholestasis in mice (in Atp8b1 mutant mice caused by CA feeding and in WT mice caused by ANIT-treatment), does not lead to itch and cannot serve as a model of cholestatic pruritus in human patients in general and PFIC type 1 patients in particular." (PMID 33731871, 2021). "In addition to PFIC1 and -2, benign recurrent forms of intrahepatic cholestasis (termed BRIC) and intrahepatic cholestasis of pregnancy have also been associated with ATP8B1 and ABCB11 mutations." (PMID 33557414, 2021). "Mutations in human ATP8B1 are associated with intrahepatic cholestasis and also cause hearing loss." (PMID 24651716, 2014). "In addition, depending on the severity of the disease, inherited intrahepatic cholestasis resulting from mutations in ATP8B1 or ABCB11 can be classified as either PFIC1 or 2, respectively, or benign recurrent intrahepatic cholestasis (BRIC) 1 or 2, respectively." (PMID 35740260, 2022). "Intrahepatic cholestasis can be induced in Atp8b1 mutant mice by feeding them a 0.1% CA supplemented semi-synthetic diet." (PMID 33731871, 2021). "Patient 3 was diagnosed with PFIC1 because of lower mRNA and protein expression of ATP8B1 in his liver specimen and because of his clinical symptoms including intrahepatic cholestasis with normal GGT, intractable itching, failure to thrive, and deafness." (PMID 25022842, 2014). "BRIC is an autosomal recessive disorder caused by the mutation of two hepatic transporter genes: the ATP8B1 gene, coding for familial intrahepatic cholestasis-1 (FIC1; BRIC type 1) and the ABCB11 gene, coding for the bile salt export pump (BSEP; BRIC type 2)." (PMID 23403701, 2013). "Our patient was found to have two variants associated with intrahepatic cholestasis: a likely pathogenic variant (ACMG class 4) in the ABCB11 gene, linked to PFIC2, and a variant of uncertain significance (ACMG class 3) in the ATP8B1 gene, which is associated with PFIC1." (PMID 41395309, 2025). "In addition to the mutations in MDR3 and BSEP genes, rare mutations within the FIC1 gene (ATP8B1) present within the bile duct membrane and the FXR gene (NR1H4) were also detected in Caucasian patients diagnosed with intrahepatic cholestasis of pregnancy." (PMID 32384779, 2020). "In patients and mice with an ATP8B1/Atp8b1 deficiency, the canalicular membrane is not stable and extraction of lipid by the detergent action of bile salts leads to formation of granular bile and intrahepatic cholestasis." (PMID 22912588, 2012). "While the molecular events in the livers of these patients are unknown, this clinical setting is consistent with our model in which statin-induced miR-33 represses both ABCB11 and ATP8B1, thus decreasing bile secretion and eventually leading to intrahepatic cholestasis." (PMID 22767443, 2012). "ATP8B1, also known as FIC1 (familial intrahepatic cholestasis 1), is an ATP-dependent membrane transport protein in the P-type ATPase family." (PMID 20126555, 2010).
benign recurrent intrahepatic cholestasis (15 papers, 2008 to 2024). Benign recurrent intrahepatic cholestasis (BRIC) is a hereditary liver disorder characterized by intermittent episodes of intrahepatic cholestasis, generally without progression to chronic liver damage. "Benign recurrent intrahepatic cholestasis (BRIC) is a disease on the spectrum of familial intrahepatic cholestasis caused by homozygous ABCB11 or ATP8B1 mutations." (PMID 37205944, 2021). "Mutations in ATP8B1 (FIC1) underlie cases of cholestatic disease, ranging from chronic and progressive (progressive familial intrahepatic cholestasis) to intermittent (benign recurrent intrahepatic cholestasis)." (PMID 20126555, 2010). "Mutations in ATP8B1 result in cholestatic disease with an autosomal recessive mode of inheritance, and ranging in severity from mild and episodic (benign recurrent intrahepatic cholestasis, BRIC1) to chronic and progressive (progressive familial intrahepatic cholestasis; PFIC1)." (PMID 20126555, 2010). "Mutations in the gene coding for ATP8B1 are known to lead to severe liver disease in humans, namely progressive familial intrahepatic cholestasis 1 (PFIC1), and benign recurrent intrahepatic cholestasis type 1 (BRIC1)." (PMID 27347675, 2016). "ATP8B1 deficiency is caused by mutations in ATP8B1, and can present as either progressive familial intrahepatic cholestasistype 1 (PFIC1) or benign recurrent intrahepatic cholestasis type 1 (BRIC1)." (PMID 27050426, 2016). "Patients with benign recurrent intrahepatic cholestasis type 1 (BRIC type 1) or progressive intrahepatic cholestasis type 1 (PEIC type 1) caused by mutations in ATP8B1 also present with progressive hearing loss, as observed in the ATP8B1 mutant mouse model." (PMID 36959542, 2023). "ATP8B1 deficiency can present with persistent cholestasis, usually at young age (progressive familial intrahepatic cholestasis; PFIC) or with episodic cholestasis at any age (benign recurrent intrahepatic cholestasis; BRIC)." (PMID 24260417, 2013). "Benign recurrent intrahepatic cholestasis type 1 (BRIC1) is a rare autosomal recessive disorder that is characterized by intermittent episodes of jaundice and intense pruritus and caused by pathogenic variants of adenosine triphosphatase phospholipid transporting 8B1 (ATP8B1)." (PMID 35572954, 2022). "ATP8B1 has been implicated in hepatic disorders such as progressive familial intrahepatic cholestasis (PFIC) and benign recurrent intrahepatic cholestasis (BRIC)." (PMID 27458383, 2016). "Genetic testing should also be considered such as mutations in the hepatobiliary transporters ATP8B1, ABCB11 and ABCB4 in the evaluation of familial hepatocellular cholestasis like progressive familial intrahepatic cholestasis (PFIC) or benign recurrent intrahepatic cholestasis (BRIC)." (PMID 39600379, 2023).
benign recurrent intrahepatic cholestasis type 1 (15 papers, 2012 to 2024). Benign recurrent intrahepatic cholestasis 1 (BRIC1) is characterized by episodes of liver dysfunction called cholestasis, during which the liver cells have a reduced ability to release a digestive fluid called bile. "BRIC type 1 is associated with mutations in the ATP8B1 gene, while BRIC type 2 is linked to mutations in the ABCB11 gene." (PMID 39735080, 2024). "Genetic defects in ATP8B1 cause progressive familial intrahepatic cholestasis 1 (PFIC1) or benign recurrent intrahepatic cholestasis 1 (BRIC1)." (PMID 38436085, 2024).
liver disease (15 papers, 2010 to 2025). "In humans, mutations in the FIC1/ATP8B1 gene cause progressive familial cholestasis, a severe liver disease with defective bile secretion and hearing loss." (PMID 22912588, 2012). "ATP8B1 variants were linked to chronic liver disease (75%); however, these variants, which had a low predicted pathogenicity, were common in patients with different underlying liver diseases." (PMID 39984942, 2025). "Our results indicate that the ATP8B1-deficient mouse in a B6 background may be a better model of human ATP8B1 deficiency and highlight the importance of informed background strain selection for mouse models of liver disease." (PMID 20126555, 2010). "Yet these two CP patients did not have any signs of liver disease or extrahepatic features of ATP8B1 deficiency other than pancreatitis." (PMID 24260417, 2013). "ATP8B1 deficiency without liver disease has been described before, suggesting that reduced penetrance of the liver phenotype can indeed be seen." (PMID 24260417, 2013). "For instance, PFIC and BRIC are both typically caused by biallelic mutations in ATP8B1 or ABCB11; however, patients with BRIC do not exhibit the severe liver disease seen in patients with PFIC." (PMID 34828443, 2021).
progressive familial intrahepatic cholestasis (11 papers, 2013 to 2024). Progressive familial intrahepatic cholestasis (PFIC) refers to a heterogeneous group of autosomal recessive disorders of childhood that disrupt bile formation and present with cholestasis of hepatocellular origin. "Progressive familial intrahepatic cholestasis (PFIC) is caused by variations in ATP8B1, ABCB11 or ABCB4 genes." (PMID 29973134, 2018). "At present, dozens of ATP8B1 pathogenic mutations have been identified that mainly cause BRIC1 and progressive familial intrahepatic cholestasis 1 (PFIC1)." (PMID 35783636, 2022). "Hereditary cholestatic syndromes in children, clinically presenting as progressive familial intrahepatic cholestasis (PFIC) types 1–3, result from mutations of ATP8B1, ABCB11, and ABCB4." (PMID 28626473, 2017).
familial intrahepatic cholestasis (10 papers, 2010 to 2023). An instance of intrahepatic cholestasis that is caused by an inherited modification of the individual's genome. "Mutations in several human P4-ATPase genes are associated with severe diseases, for example in ATP8B1 causing progressive familial intrahepatic cholestasis, a rare inherited disorder progressing toward liver failure." (PMID 35416773, 2022). "Genes associated with familial intrahepatic cholestasis (FIC) include ATP8B1 (FIC1), ABCB11 (FIC2), ABCB4 (FIC3), TJP2 (FIC4), NR1H4 (FIC5) and MYO5B (FIC6)." (PMID 33557414, 2021). "Among the 14 P4-ATPases, mutations of ATP8B1 (FIC1) have been reported to cause familial intrahepatic cholestasis." (PMID 24957965, 2012). "For example, ABCB11 or ATP8B1 causing progressive familial intrahepatic cholestasis; other genes might lead to liver abnormalities that are presenting clinically as a secondary cause." (PMID 38057357, 2023). "Mutations in the ATP8B1, ABCB11 and in the ABCB4 genes encoding ATP8B1, BSEP and MDR3 respectively, have been linked to progressive familial intrahepatic cholestasis." (PMID 36430444, 2022). "The gastroenterologist suggested progressive familial intrahepatic cholestasis, and ATP8B1 gene sequencing was recommended." (PMID 33912394, 2021).
Cholestatic liver disease (9 papers, 2010 to 2026). "Its ability to treat progressive cholestatic liver disease associated with trafficking defects in canalicular membrane proteins has recently been demonstrated in selected patients with BSEP deficiency or ATP8B1 deficiency." (PMID 26900700, 2016). "Genetic analysis using next-generation sequencing included a panel of five genes involved in cholestatic liver diseases (ATP8B1, ABCB11, ABCB4, ABCC2 and MYO5B)." (PMID 41797682, 2026). "We report a case of congenital MyoD with combined heterozygous ATP8B1/ABCB4 mutation who developed chronic, progressive low gamma-glutamyltransferase cholestatic liver disease at early infancy, and eventually underwent successful liver transplantation." (PMID 37206451, 2021). "To examine the translational potential of the findings in Atp8b1IEC-KO mice, we conducted a nationwide Japanese survey to identify patients with PFIC1, an extremely rare pediatric cholestatic liver disease resulting from a genetic defect of ATP8B1, and collected their plasma." (PMID 37990006, 2023). "Interestingly, ATP8B1 was expressed equally in all 3 cholestatic liver disease groups (PSC, adult cholestatic liver disease other than PSC, and the PFIC3 group, data not shown)." (PMID 31886153, 2019). "We have previously shown that mice lacking Atp8b1 exhibit a mild form of human ATP8B1 deficiency, but do not suffer from progressive cholestatic liver disease; most of this work was performed in 129 mice." (PMID 20126555, 2010).
pneumonia (8 papers, 2013 to 2025). An acute, acute and chronic, or chronic inflammation focally or diffusely affecting the lung parenchyma, caused by an infection in one or both of the lungs (by bacteria, viruses, fungi, or mycoplasma.). "Mutations in ATP8B1 are responsible for liver cholestasis, and affected individuals are more susceptible to pneumonia." (PMID 34659373, 2021). "Mutations in the ATP8B1 are responsible for liver cholestasis (BRIC1, PFIC1), and affected individuals are more susceptible to pneumonia." (PMID 34659373, 2021). "For instance, patients with ATP8B1 deficiency present with severe chronic liver disease but are also susceptible to pneumonia." (PMID 27628304, 2017). "Further, mutation in Atp8b1 or lung inflammation is associated with increased secretion of cardiolipin in airways and also development of pneumonia." (PMID 27689529, 2016). "Furthermore, Atp8b1 deficiency is associated with pancreatitis, secretory diarrhoea, growth retardation, hearing impairment, hypothyroidism, and pneumonia." (PMID 36273194, 2022). "Atp8b1 mutant mice carrying the mutation in the membrane-bound transporter showed decreased lung function and had an increased susceptibility to bacterial-induced pneumonia and epithelial cell apoptosis." (PMID 27689529, 2016). "However, it remains unclear whether ATP8B1 is a cardiolipin transporter and whether susceptibility to pneumonia in ATP8B1 deficient patients results from a defect in cardiolipin transport." (PMID 23579954, 2013). "While the role of Atp8b1 in pneumonia-induced acute lung injury (ALI) has been well studied, its potential role in oxidative stress-induced ALI is poorly understood." (PMID 30636723, 2019). "Atp8b1 mutant mice and humans with pneumonia have elevated levels of cardiolipin in lung fluid, which disrupts the function of the surfactant." (PMID 27689529, 2016).
Hepatic steatosis (6 papers, 2016 to 2025). Steatosis is a term used to denote lipid accumulation within hepatocytes. "Because intestinal ATP8B1 deficiency is known to cause hepatic steatosis, we focused on the effect of ATP8B1 deficiency on glucose metabolism." (PMID 40851490, 2025). "Notably, 60%–90% of post‐transplant PFIC1 patients develop hepatic steatosis or steatohepatitis, a condition recently linked to intestinal deficiency of ATP8B1." (PMID 40851490, 2025). "Hence, the hepatic steatosis observed in our mice may thus be caused by intestinal deficiency of ATP8B1." (PMID 40851490, 2025). "Second, hepatic steatosis in Atp8b1 mutant liver coincided with increased expression of Cd36, which is involved in the uptake of medium‐ and long‐chain fatty acids." (PMID 40851490, 2025). "In the present study, we observed hepatic steatosis in non‐cholestatic, male Atp8b1 whole body mutant mice, which highly resembles graft steatosis in PFIC1 patients after liver transplantation." (PMID 40851490, 2025). "Because graft steatosis in post‐transplant PFIC1 patients can be prevented or reversed by internal biliary diversion effectively, the (unaffected) enterohepatic cycling of bile salts in the Atp8b1 mutant mice likely contributes to the development of hepatic steatosis." (PMID 40851490, 2025). "An overt difference between Atp8b1 mutant mice and PFIC1 patients is hepatic steatosis, which is not observed in pre‐transplant PFIC1 patients but is strikingly prevalent in post‐transplant PFIC1 patients." (PMID 40851490, 2025).
liver failure (5 papers, 2010 to 2025). A liver disease characterized by the liver losing or has lost all of its function. "Patients with severe ATP8B1 deficiency (i.e. PFIC1) typically require liver transplantation prior to adulthood, due to liver failure." (PMID 20126555, 2010). "PFIC represents a group of disorders (with subtypes grouped based on the underlying genetic deficiency; eg ATP8B1‐deficient PFIC, ABCB11‐deficient PFIC) in which disruption of bile homeostasis can eventually lead to cholestasis, cirrhosis, liver failure and death." (PMID 32492754, 2020).
pancreatitis (5 papers, 2009 to 2023). Inflammation of the pancreas. "Our findings are compatible with a model in which CP can be caused by mutations in ATP8B1 on both alleles, which is in line with the frequent occurrence of pancreatitis in patients with ATP8B1 deficiency." (PMID 24260417, 2013). "In this respect ATP8B1 is an interesting candidate due to its strong expression in the pancreas, its supposed general function in membrane organization and the higher incidence of pancreatitis in patients with ATP8B1 deficiency." (PMID 24260417, 2013). "Extrahepatic manifestations such as diarrhoea, pancreatitis and hearing loss can be observed in patients with ATP8B1 deficiency." (PMID 24260417, 2013). "As the incidence of pancreatitis is higher in patients with ATP8B1 deficiency, we hypothesized that mutations in this gene might also be associated with CP." (PMID 24260417, 2013). "Pancreatitis might even be the only symptom in patients with ATP8B1 deficiency." (PMID 24260417, 2013). "However it suggests that pancreatitis might be the first or sole symptom of ATP8B1 deficiency." (PMID 24260417, 2013). "However, for those with FIC1 disease, liver transplant can lead to further complications such as pancreatitis, allograft steatosis, and diarrhea related to extrahepatic expression of ATP8B1." (PMID 38055640, 2023).
steatosis (5 papers, 2022 to 2025). Increased lipid within the cytoplasm of cells. "The steatosis of graft livers in PFIC1 patients is presumably caused by extra‐hepatic ATP8B1 deficiency." (PMID 40851490, 2025). "Still, we cannot exclude that increased hepatic PDE4D expression and impaired glucagon‐cAMP signalling contribute to hepatic steatosis in Atp8b1 mutant mice." (PMID 40851490, 2025). "Notably, PDE4D overexpression in mouse liver increased CD36 expression, suggesting that the PDE4D‐CD36 axis might contribute to the hepatic steatosis observed in Atp8b1 mutant mice." (PMID 40851490, 2025).
Cirrhosis (4 papers, 2022 to 2025). A chronic disorder of the liver in which liver tissue becomes scarred and is partially replaced by regenerative nodules and fibrotic tissue resulting in loss of liver function. "Although cirrhosis of PFIC1 livers could contribute to decreased hepatic glycogen levels, a trend of enhanced compensatory glycogenolysis was also observed in the (non‐cirrhotic) livers of Atp8b1 mutant mice." (PMID 40851490, 2025).
hepatocellular carcinoma (4 papers, 2019 to 2025). A malignant tumor that arises from hepatocytes. "A study using hepatocellular carcinoma cells HepG2 showed that ATP8B1 knockdown in HepG2 cells leads to a strong increase in the mitochondrial oxidative phosphorylation without a change in glycolysis, which coincided with increased mitochondrial fragmentation and phosphatidylethanolamine levels." (PMID 37686603, 2023).